CD4 (CD4 molecule)
Diseases named in the same sentence as CD4 in open-access papers (continued):
Sharing a sentence is not in itself a finding about the gene and the disease.
colitis (continued). "The results showed that DSF and Cu2+ significantly decreased the proportion of IL-17+ CD4+ T cells in DSS-induced colitis." (PMID 37284442, 2023). "In vivo DCA treatment (2g/L, ad libitum) significantly reduces CD4+ T cell accumulation, especially Th17 cells, in the spleen and mesenteric lymph nodes in a naive T cell adoptive transfer colitis model." (PMID 37809060, 2023). "We and others have demonstrated an important regulatory activity of epithelium-adapted CD4+ T cells in the context of response to diet, or in the context of colitis or infection." (PMID 37191720, 2023). "NK1.1−NKG2D+CD4+T cells delayed the onset of DSS-induced colitis, and their protective effect was dependent on transforming growth factor beta (TGF-β)." (PMID 38139373, 2023). "Extract from mango mistletoes Dendrophthoe pentandra alleviates trinitrobenzene sulfonic acid-induced colitis via modulating CD4+ T cells." (PMID 37693835, 2023). "To investigate the clinical effect of tofacitinib in mice, we performed a CD4+ transfer colitis into lymphopenic Rag2−/− mice and treated the mice with tofacitinib dissolved in the drinking water." (PMID 36882462, 2023). "In contrast, the co‐administration of Pg and LGG‐stimulated CD4+T cells mitigated colitis by reducing the Th17/Treg ratio." (PMID 37904683, 2023). "To characterize the impact of MKO on lymphocytes, we detected the subtypes of lymphocytes and found the percentage of CD4+ T cells was significantly higher in the colon lamina propria in MKO colitis mice than that in WT colitis mice." (PMID 36635421, 2023). "In a recent study, the proliferation of Tregs and elimination of microbiota-specific CD4+ T cell activation through metabolic checkpoint inhibition protected against colitis." (PMID 38107848, 2023). "In wild-type group, we found that 9 of the 15 cell types were aberrantly changed during colitis, including fibroblasts, enterocytes, goblet cells, neutrophils, monocytes, CD4+ T cells, γδ T cells, ILC1 and ILC2." (PMID 36792629, 2023). "Increased infiltration of CD8+ lymphocytes is recognized as a specific feature of CIC and an increased CD8+/CD4+ ratio has been proposed as a simple biomarker and discriminator with respect to other forms of colitis." (PMID 37511260, 2023). "Here, we reveal that deletion of RNA 5-methylcytosine (m5C) methyltransferase Nsun2 in mouse CD4+ T cells specifically inhibits Th17 cell differentiation and alleviates Th17 cell-induced colitis pathogenesis." (PMID 36792629, 2023). "Among these immune cells, activated CD4 T, Th1, and Th17 cells were observed in the epithelial layer of the colon of patients with colitis." (PMID 38077339, 2023). "Conversely, the transfer of CD4+ T cells from St6gal1+/+ UC rats aggravated the symptoms of colon inflammation." (PMID 37424034, 2023). "This further suggests that the contribution of unopposed STAT3α to DSS-induced colitis in CD4+ cells supersedes its contribution in myeloid and/or epithelial cells." (PMID 37296943, 2023). "IL-6 production by lamina propria macrophages and CD4+ cells is increased in the experimental colitis and in IBD patients." (PMID 35832050, 2022). "Using IFN-γ-deficient RAG−/− recipients, IFN-γ was subsequently shown to be dispensable for the induction and progression of CD4+CD25−CD45RBhigh T cell transfer colitis." (PMID 36012618, 2022). "Together, these data indicate that following mucosal injury, TAGAP deficiency was associated with increased IL-17A-producing and IFN-γ-producing CD4+ T cells infiltration and proinflammatory gene expression, which greatly exacerbated colitis severity." (PMID 36704549, 2022). "IL-36R expression on CD4+ T cells was found to promote intestinal pathology in a murine model of colitis." (PMID 35177818, 2022). "We isolated DAPI−CD45+CD3+CD4+CD8− cells from the ceca of R23FR mice with colitis (Day 56) and from control FR mice (Day 56), cocultured them with IECs, and measured cell survival using a CellTiter-Glo Luminescent Cell Viability Assay Kit." (PMID 35468944, 2022).
colitis (continued). "By contrast, transferred lhh KO CD4+ T cells were strongly impaired in their ability to induce colitis and mice showed minimal signs of inflammatory disease in the colon." (PMID 35835905, 2022). "Colitis mice treated with Trichinella spiralis extracellular vesicles (Ts-Evs) showed a significant increase in the CD4+IL-4+ cell populations compared to the TNBS group, which was associated with ameliorating colitis by the expansion of Th2 cells." (PMID 35741032, 2022). "During co-housing with NOD2−/− mice, acquisition of Rickenellaceae by wild-type mice was associated with increased proportions of CD4+LAP+Foxp3− T cells and less severe TNBS-colitis." (PMID 36012618, 2022). "Another interesting study in primates demonstrated that the experimental administration of Trichuris trichiura can ameliorate colitis by both induction the colonic CD4+ T cells producing IL-4 and modulation of microbial populations." (PMID 35435504, 2022). "This immune response is mediated by CD4+ T cells, but mechanistic insights into how these CD4+ T cells trigger and perpetuate colitis have remained elusive." (PMID 35468944, 2022). "It has been shown that mPGES-1 is detected with COX-2 to some extent in the colonic lamia propria in T cell–driven colitis induced by adoptive transfer of CD4+ effector T cells in mice." (PMID 34983695, 2022). "In this study, we report a mechanism whereby IL-36α promotes the development of colitis through driving the generation of colitogenic CD4+ T cells." (PMID 35177818, 2022). "Lack of P2ry10 and P2ry10b provided lower responsiveness to LysoPS for CD4+ T cells, which led to suppression of LysoPS-dependent aggravation of colitis." (PMID 35608941, 2022). "Amiselimod, a novel, more selective S1P1 receptor-modulating compound improved the clinical and histological score of colitis in a CD4+CD45RB+ T-lymphocyte adoptive transfer model by reducing the infiltration of Th1 and Th17 cells in the colonic mucosa." (PMID 35163775, 2022). "Since this model is associated with an increase in highly activated T cells and as such T cells play an essential role in TNBS colitis, it is suitable for ascertaining CD4+T cell-dependent immunity in the inflammatory bowel." (PMID 36304936, 2022). "To address this, we used the T cell transfer model of colitis, in which Rag1−/− mice undergo T cell driven colitis when CD4+ T effector cells are adoptively transferred from donor wt mice, in the absence of Tregs." (PMID 35177818, 2022). "Colitis-inducing CD4+ (memory) T cells are found in the mesenteric lymph nodes (mLNs) during remission and are able to trigger disease when transferred to lymphopenic mice (Rag1−/−), but only upon Red 40 treatment." (PMID 35468944, 2022). "The administration of T. halophilus to DSS-induced colitis mice also increased the frequencies of IL-10+ cells in CD4+ T cells (36.31 ± 10.62% vs. 12.61 ± 4.45%, p < 0.05) and CD8+ T cells (38.97 ± 9.79% vs. 13.26 ± 6.74%, p < 0.05)." (PMID 35741032, 2022). "As we have identified a potential mechanism whereby IL-36 promotes colitis via the enhanced gut homing potential of pro-inflammatory Th1 cells in mice, we next sought to investigate what effect IL-36 has on human CD4+ T cell responses." (PMID 35177818, 2022). "Abnormal CD4+ TEM cell activation and expansion is associated with the development of colitis, which ultimately contributes to the pathogenesis of CAC." (PMID 36045676, 2022). "Here, we showed that CD4+ TRM cells were expanded in the colon of mice with dextran sulfate sodium (DSS)–induced colitis." (PMID 35844584, 2022). "Polysaccharide A of B. fragilis mediates the conversion of CD4+ T cells into Foxp3+ Treg cells and is capable of reversing experimental colitis in mice." (PMID 36584066, 2022). "If mice develop the colitis in 4 weeks, induced by co-injected naive conventional CD4+ T cells, it would indicate that Treg cells from Rbx1-deficient mice have lost suppression function, and vice versa." (PMID 35641500, 2022).
colitis (continued). "TIGIT deficiency impairs IL-17A production in CD69+CD103− CD4+ TRM cells specifically, resulting in lower disease activity index and reduced pathological injury in mice with DSS-induced colitis." (PMID 35844584, 2022). "Consistently, Foxp3Cre-YFPSetd2 f/f mice had more weight loss and shortened colons in TNBS-induced colitis, accompanied by enhanced IFN-γ production by CD4+ T cells in the colon." (PMID 36463230, 2022). "Another compound that targets S1P1/3/5 receptors, etrasimod, attenuated disease activity in the CD4+CD45RB+T-cell adoptive transfer colitis mouse model and demonstrated therapeutic efficacy in a phase 2 clinical trial of patients with UC." (PMID 35163775, 2022). "Our further data revealed that TIGIT expression was notably increased in CD4+ T cells from DSS-induced colitis." (PMID 35844584, 2022). "Ozanimod was shown to induce the internalization and degradation of these receptors, improve the histological score in mice with TNBS (and adoptive CD4+CD45RB+T-cell transfer mediated) colitis and reduce the numbers of circulating B and CCR7+ T-lymphocytes." (PMID 35163775, 2022). "Taken together, these results suggest an increased ability of PTEN-/- DCs to express costimulatory signals during colitis, thereby driving Th1 responses and CD4+ T cell infiltration into the gut." (PMID 35514976, 2022). "In a CD4+CD45RBhi T cell adoptive transfer mouse model of colitis, it has been shown that these MLN DC subsets lose their regulatory function and acquire a more proinflammatory phenotype." (PMID 35163775, 2022). "In support of our aGVHD findings, we observed that both Fli1fl/WTCre+ and Fli1fl/flCre+ naive CD4+ T cells had a reduced ability to induce colitis, in which Fli1fl/WTCre+ CD4+ T cells showed the least pathogenicity in colitis development." (PMID 36074578, 2022). "In particular, studies examining mouse and human colonic tissue have reported on IL-17A+ CD4+ T cell or IFNγ+IL-17A+ CD4+ T cell populations that has been shown to exacerbate colitis severity." (PMID 36704549, 2022). "Naïve CD4+ T lymphocytes are known to induce severe colitis when transferred to Rag2 knockout (KO) mice." (PMID 35707543, 2022). "Here, we showed that TIGIT was required for IL-17A production by CD69+CD103− CD4+ TRM cells during DSS-induced colitis." (PMID 35844584, 2022). "Total CD4+ T cells were significantly increased in DSS-induced colitis mice compared to control mice." (PMID 36159798, 2022). "IL-17A expression in CD69+CD103− CD4+ TRM cells was impaired in TIGIT−/− mice during the induction of colitis." (PMID 35844584, 2022). "Treatment with IPI has been shown to increase the diversity of the CD4+ T cell repertoire, leading to potential autoreactive populations that, in turn, contribute to the pathogenesis of colitis." (PMID 36173679, 2022). "Using a mouse CD4+CD45RBHigh T cell transfer model for colitis, the group demonstrated that the transfer of CD4+CD25+ T cells ameliorated both clinical and histological signs of colitis after a single infusion." (PMID 36466912, 2022). "Studies indicate that CD4+CD8α+ IELs protect against autoimmune colitis in a food allergy model, and exacerbated colitis is observed on re-encountering the cognate or bacterial antigen; however, their precise role in the intestine is unclear." (PMID 36353619, 2022). "Nine clusters were revealed by unbiased clustering of cecal CD4+ T cells from a pool of samples from 3 mice with colitis (6388 cells)." (PMID 35468944, 2022). "Co-administration of peritoneal IL-10 competent B cells also reduced the severity of colitis induced by the intraperitoneal administration of CD25-CD45RBhi CD4 + T cells." (PMID 35672305, 2022). "CD69+CD103− CD4+ TRM cells are the major source of IL-17A production in the colon of mice with DSS-induced colitis." (PMID 35844584, 2022).
colitis (continued). "And CD4+ T cells stimulated with P. gingivalis and Lactobacillus rhamnosus GG were found to alleviate colitis by reducing the Th17/Treg ration via JAK-STAT signaling pathway." (PMID 36467726, 2022). "TCRαβ+CD8αα+ IELs inhibit the onset of colitis evoked by primary splenic TCRαβ+CD4+CD45RBhi T cells in an IL-10 dependent manner." (PMID 34999729, 2022). "Here, [89Zr]Zr-malDFO-GK1.5 cDb detected CD4+ T cells in the distal colon of dextran sulfate sodium-induced colitis in a mouse model of inflammatory bowel disease." (PMID 36114433, 2022). "For T cell transfer model, colitis was induced with intraperitoneal injection of CD4+CD45RBhigh T cells from donor mice." (PMID 36405760, 2022). "During DSS-induced colitis, selenium also increased IL-10 production in CD4+ T cells, reducing colonic inflammation." (PMID 35529463, 2022). "We next dissected the potential mechanisms whereby Gpr65 confines colitis and regulates the differentiation of CD4+ T cell." (PMID 35343079, 2022). "Here, we show that IL-23 expression leads to the development of colitis upon Red 40 administration and that cytotoxic CD4+ T cells are the major population driving disease development." (PMID 35468944, 2022). "CD69+CD103− CD4+ TRM cells accounted for 62.9% and 72.5% of IL-17A+ CD4+ T cells in the colon of DSS-induced colitis or control mice, representing the major source of IL-17A production." (PMID 35844584, 2022). "Colitis was reversed by depleting colitogenic T cells with anti-CD4 antibodies, leading to decreased leukocyte infiltration to sites of inflammation and reduced serum and colonic TNF-α concentrations." (PMID 35939430, 2022). "Therefore, we decided to examine whether MLN CD25+CD4+ T cells from DSS-treated Yeti/CD1d KO mice (mostly Foxp3− populations) can increase susceptibility to DSS-induced colitis compared to CD25+CD4+ T cells (primarily Foxp3+ populations) from DSS-treated CD1d KO mice." (PMID 36499642, 2022). "To examine the effect of PAMK on the Th17/Treg cell balance in DSS-induced colitis mice, we measured the proportions of both Th17 cells and Treg cells in the CD4+ T cells compartment of the MLN and spleen by flow cytometry." (PMID 36341374, 2022). "Consistent with previous findings showing that glycolysis promotion in effector T cells is a cause of severe colitis, LysoPS exaggerates large intestinal inflammation by fueling glycolysis in IFN-γ–producing CD4+ T cells." (PMID 35608941, 2022). "Here, it was demonstrated that clonally expanded OVA-specific Tr1 cells were able to prevent colitis in the CD4+CD45RBhigh adoptive transfer mouse model in an antigen-specific manner." (PMID 36389662, 2022). "An IL-10 dependent protective role of TCRαβ+CD8αα+ IELs was reported in the colitis of SCID mice induced by CD4+CD45RBhiTCRαβ+ thymus-derived T cells." (PMID 34999729, 2022). "Stimulation of CD4+ T cells to produce IL-10 inhibits the inflammatory response in the process of colitis." (PMID 35794311, 2022). "In samples from the lamina propia, these patients had predominantly CD8+ T cells at the time of refractory colitis and higher CD4 FoxP3 + after FMT." (PMID 35474500, 2022). "TIGIT deficiency led to decreased numbers of CD69+CD103− and CD69+CD103+ CD4+ TRM cells in the colon during DSS-induced colitis." (PMID 35844584, 2022). "Rather, as evidenced by the tendency of TLR5 knockout mice to develop colitis, flagellin contributes to negatively regulating the response to gut microbiota via IL-10 production and by stimulating regulatory CD4+ T cells." (PMID 36555214, 2022). "A previous study reported that DSS-induced colitis can be induced in mice depleted of CD4+ helper T cell by the treatment with CD4 monoclonal antibody." (PMID 34983695, 2022). "Among the lymphocytes, CD4+ T cells particularly increased in the recovery stage after acute DSS colitis and stayed high during chronic disease stages." (PMID 36009449, 2022).
colitis (continued). "Administration of GSK-J4, a histone demethylase inhibitor, resulted in the retinoic acid-mediated induction of tolerogenic DCs in the dextran sulfate sodium (DSS) colitis mouse model with concomitant production of IL-10 by CD4+ T cells." (PMID 36389662, 2022). "For the first time, our data revealed the heterogeneity of CD4+ TRM cells in the colon of mice with DSS-induced colitis." (PMID 35844584, 2022). "In this study, we evaluated CDK9 inhibition in adaptive immune-mediated colitis and explored its effect on the transcriptional landscape and effector function of colonic CD4+ T cells from patients with IBD." (PMID 35660024, 2022). "Administration of T. halophilus in mice with DSS-induced colitis upregulated the frequencies of IL-4+ cells in CD4+ T cells (51.27 ± 4.58% vs. 23.96 ± 9.40%, p < 0.001) and in CD8+ T cells (37.27 ± 90% vs. 16.93 ± 6.88%, p < 0.001)." (PMID 35741032, 2022). "For instance, lymphoid nodules in the rectum that resemble PPs and contain elevated numbers of macrophages; CD4+ and CD8+ T-cells in mice with DSS-induced colitis, were linked with proximal disease extension." (PMID 35163775, 2022). "IL-10 produced by intestinal CD4+ T cells is responsible for maintaining immune homeostasis, thereby inhibiting colitis development." (PMID 36590200, 2022). "In 2006, although Japanese peers had found that FTY720 suppresses CD4+CD44highCD62L− effector memory T cell to treat experimental colitis, the effect of memory T cells is rarely reported in the human UC." (PMID 35388299, 2022). "In the present study, we found that the proportion of DP CD4+CD8+ T cells was significantly decreased in the inflamed colonic tissues in the DSS-induced colitis model." (PMID 35761286, 2022). "Essential roles of CD4+ T cells have been demonstrated in several animal models of experimental colitis, most notably in the adoptive transfer of naïve T cells into lymphopenic hosts." (PMID 35468944, 2022). "Here, our data revealed TIGIT expression in CD4+ T cells from LPMC was notably increased in mice with DSS-induced colitis." (PMID 35844584, 2022). "In conclusion, our study demonstrated a elevation of CXCL13 in both IBD patients and DSS-induced colitis mice, which contributed to the recruitment of CD4+CXCR5+ T cells to secondary lymphoid organs, thereby promoting the production of regulatory CD5+ B cells." (PMID 36172372, 2022). "Flow cytometry analysis showed that CD226 expression was increased in CD4+ T cells from spleens in DSS-induced colitis." (PMID 35844584, 2022). "Deletion of GLUT1 reduced CD4+-T-cell glycolytic activity, and at the same time, it impaired effector CD4+-T-cell generation and mitigated the severity of colitis." (PMID 35883539, 2022). "CD69+CD103− CD4+ TRM cells are the major source of IL-17A production in the gut of mice with DSS-induced colitis." (PMID 35844584, 2022). "In the present study, colonic expressions of IL-1β and IL-6, major macrophage-related proinflammatory cytokines relevant to IBD, were still exacerbated in mPGES-1−/− mice under the CD4+ T cell depletion during colitis." (PMID 34983695, 2022). "Following the adoptive transfer of naïve CD4+ CD25- CD62L+ CD44low T cells into Rag2-/- mice, colitis ensued by day 30, with mice suffering weight loss and diarrhea." (PMID 35660024, 2022). "PSA is also sufficient to suppress interleukin-17 and protect from experimental colitis in a mouse model infected with Helicobacter hepaticus, again by acting on CD4+ T cell populations." (PMID 36071979, 2022). "Another study found higher proportion of CD8 T cells in anti-PD-1-induced colitis versus greater CD4 T cells in anti-CTLA-4-induced colitis." (PMID 35474500, 2022). "LP CD4+LAP+ T cells are regulatory T cells that ameliorate colitis by exerting corresponding immune effects." (PMID 35954484, 2022). "Intriguingly, in colitis mice, after resveratrol treatment, the percentage of CD4+ T cells in MLNs is restored to normal level, but decreases these cells in the colon LP." (PMID 35369090, 2022).